IQGAP1 (IQ motif containing GTPase activating protein 1)
Diseases named in the same sentence as IQGAP1 in open-access papers (continued):
Sharing a sentence is not in itself a finding about the gene and the disease.
liver cancer (continued). "The efficacy of IQGAP1 silencing using shRNA as an innovative therapeutic target for curing mouse hepatic cancer induced by DENA was investigated." (PMID 36276098, 2022). "Inhibiting IQGAP1 expression reduced cell proliferation, migration, and EMT, and increased apoptosis in liver cancer cells, indicating the importance of IQGAP1 in liver cancer cell maintenance." (PMID 34439095, 2021). "IQGAP1 also contributes to liver cancer through Wnt signaling, in which IQGAP1 interacts directly with β-catenin and regulates β-catenin-dependent transcription, impacting cell proliferation and migration." (PMID 34439095, 2021). "Bile acid is a common factor in liver cancer and upregulates the Hippo pathway both in vitro and in vivo in an IQGAP1-dependent manner." (PMID 34439095, 2021). "In the presence of active Wnt and MET signaling, overexpression of IQGAP1 promotes the formation of highly aggressive liver cancer." (PMID 34439095, 2021). "In liver cancer cells, the bile acid-induced overexpression of IQGAP1 decreased YAP1′s phosphorylation, which inhibits both YAP1-p73 regulated transcription of apoptosis-related genes and pro-growth YAP1-TEAD transcription." (PMID 34439095, 2021). "While IQGAP2 and -3 expression is restricted to specific organs, IQGAP1 is ubiquitously expressed and has been shown to be deregulated in different tumour types such as liver cancer, where it behaves as a putative oncogene." (PMID 33672268, 2021). "This was also observed in human liver cancer whereby IQ motif containing GTPase activating protein 1 (IQGAP1) and vimentin were upregulated." (PMID 31963677, 2020). "For liver cancer, the expression of IQGAP1 was found increased in HCC and it was believed to promote cell proliferation by the activation of Akt." (PMID 24763314, 2014). "In contrast, IQGAP1 is overexpressed in more aggressive liver cancer cell lines and the majority of HCC specimens." (PMID 20977743, 2010). "The most recent research confirms IQGAP1’s involvement in liver cancer invasion." (PMID 36276098, 2022). "More studies are needed to determine whether IQGAP1 contributes to liver cancer via the Hippo pathway." (PMID 34439095, 2021). "Briefly, levels of IQGAP1 are commonly increased while IQGAP2 levels are decreased in liver cancer." (PMID 34439095, 2021). "In particular, our work may explain, at least in part, the effect that IQGAP1 has in liver cancer, where this protein is commonly overexpressed and is proposed to behave as an oncogene." (PMID 33672268, 2021). "Further studies investigating the different roles of IQGAP1 in epithelial carcinoma cells vs. in stromal cells could lend additional insight into how IQGAP1 contributes to primary liver cancer and to liver metastases." (PMID 34439095, 2021). "The results confirmed that the destruction of IQGAP1 with sgIQ 1.1 loaded HN3LC9-293exo plus sorafenib could induce efficient apoptosis in liver cancer cells HuH-7." (PMID 33062407, 2020). "Therefore, the silencing of IQGAP1 could be part of a promising therapeutic strategy against hepatic cancer." (PMID 36276098, 2022). "Therefore, we will use RNA interference (RNAi) technology to silence IQGAP1 oncogene to completely recover the chemically induced models for hepatic cancer by designing short RNAi specific for IQGAP1 gene in HCC cells in vivo and construct new vectors suitable for this purpose." (PMID 36276098, 2022). "Moreover, an involvement of IQGAP1 in YAP1-driven oncogenesis was proposed in liver cancer." (PMID 33672268, 2021). "A previous study had already shown that IQGAP1 may promote liver cancer through YAP1 signalling." (PMID 33672268, 2021). "Hence, IQGAP1 is considered to be one of the important targets in liver cancer therapeutics." (PMID 33062407, 2020). "High IQGAP1 expression typically indicates poor HCC prognosis, whereas the absence of both IQGAP1 and IQGAP2 exhibits a protective mechanism against liver cancer." (PMID 41035668, 2025).
liver cancer (continued). "In this study, we have methodically estimated the mechanisms and functions of the IQGAP1- shRNA in a mouse model of HCC and discussed the existing gaps and the future direction for studies on liver cancer-related IQGAP1-shRNA." (PMID 36276098, 2022). "However, IQGAP1 alone is not sufficient to cause liver cancer." (PMID 34439095, 2021). "We showed that a reciprocal relationship existed between IQGAP1 and IQGAP2 expression in human liver cancer cell lines." (PMID 20977743, 2010). "We determined the relative amounts of IQGAP1 and IQGAP2 in a panel of human liver cancer cell lines." (PMID 20977743, 2010). "Moreover, this application aimed at determining the outcome of inhibiting the IQGAP1 gene and, consequently, its effect upon Il-8 and its receptor family genes, caspases (3 and 9), BAX, Bcl-2, and TRAIL-induced apoptosis in the mouse liver cancer." (PMID 36276098, 2022). "Nonetheless, to the best of our information, there are no studies focusing on the IQGAP1-knockdown involvement in the inhibition of hepatic cancer in mice." (PMID 36276098, 2022). "Both IQGAP1 and the related protein IQGAP2 significantly impact the development of liver cancer." (PMID 34439095, 2021). "The role of IQGAP1 and IQGAP2 in liver cancer has been reviewed previously." (PMID 34439095, 2021). "Despite this, we found that cell lines derived from haematologic malignancies exhibit higher IQGAP2 levels than liver cancer cell lines, which does not occur for IQGAP1 and IQGAP3." (PMID 34034707, 2021). "IQGAP1 and IQGAP2 expression was reciprocally altered in 6/6 liver cancer cell lines." (PMID 20977743, 2010). "Immunostaining of IQGAP1 and IQGAP2 may aid in the diagnosis of HCC, and their pharmacologic modulation may represent a novel therapeutic strategy for the treatment of liver cancer." (PMID 20977743, 2010). "Altogether, these results, strongly confirm that knock-out of IQGAP1/FOXM1 with sgIF loaded HLC9-EVs + sorafenib in effect reduces CD133+ CSCs and reverses sorafenib resistance, and hence stands as promising novel therapeutic approach for thriving liver cancer treatments in the future." (PMID 37202772, 2023). "Interestingly, the absence of IQGAP1 modestly increases tumorigenesis in a carcinogen-induced liver cancer model, which may be due to increased levels of MET receptor kinase signaling." (PMID 34439095, 2021).
colorectal cancer (13 papers, 2004 to 2025). A primary or metastatic malignant neoplasm that affects the colon or rectum. "IQGAP1 is implicated in the development and progression of colorectal cancer and is highly associated with cellular invasiveness, though the precise mechanisms are not yet fully understood." (PMID 41035668, 2025). "Similarly, the cytosolic expression of IQGAP1 in colorectal cancer was associated with its pro-oncogenic functions." (PMID 33498739, 2021). "The development, metastasis, and clinical drug resistance of colorectal cancer are all closely related to the IQGAP1/ERK pathway." (PMID 41035668, 2025). "Targeted therapies focusing on the ERK signaling pathway and IQGAP1 provide new directions for the treatment and prognosis of colorectal cancer." (PMID 41035668, 2025). "We have found that the SUMOylated IQGAP1 is increased in human colorectal carcinoma and IQGAP1 SUMOylation enhances colorectal cancer progression via activating AKT-ERK signaling." (PMID 38566133, 2024). "As an example of our recent findings, it has been confirmed another adaptor protein IQGAP1 is much SUMOylated in colorectal cancer." (PMID 37528485, 2023). "PLS1 has been reported to promote metastasis of colorectal cancer through the IQGAP1/Rac1/ERK pathway." (PMID 36895481, 2023). "The SUMOylated IQGAP1 enhances colorectal cancer cell growth, cell migration and tumorigenesis in vitro and in vivo through activating the phosphorylation of ERK, MEK and AKT." (PMID 37528485, 2023). "Similar mechanism is also used for IQGAP1 to suppress colorectal cancer liver metastasis via targeting tumor stroma." (PMID 33498739, 2021). "PLS1 drives metastasis of colorectal cancer through the IQGAP1/Rac1/ERK pathway and promotes osteoblast differentiation by regulating intracellular Ca2+." (PMID 34290731, 2021). "It has been observed that IQGAP1 was over-expressed and membrane localized distinctly in various tumors, such as liver, breast, lung, gastric, ovarian, and colorectal cancers." (PMID 24763314, 2014). "IQGAP1’s involvement in colorectal cancer is closely related to the ERK pathway." (PMID 41035668, 2025). "We report the pattern of cellular and subcellular expression of scaffoldins angiomotin-like 2 (AmotL2), FK506 binding protein 5 (FKBP51) and IQ motif containing GTPase-activating protein 1 (IQGAP1) in colorectal cancer (CRC) and metastases in liver resected after oxaliplatin-based chemotherapy (CT)." (PMID 28441737, 2017). "One study found that CGN c.3560C>T triggers IQGAP1 overexpression and activates Rac1-dependent EMT, promoting the initiation and metastasis of colorectal cancer." (PMID 41035668, 2025). "IQGAP1 interacts with ARF1, contributing to ERK reactivation in vemurafenib-resistant colorectal cancer." (PMID 41035668, 2025).
melanoma (13 papers, 2015 to 2025). A malignant, usually aggressive tumor composed of atypical, neoplastic melanocytes. "MIRAT has been demonstrated to bind and stabilize cytoplasmic scaffold protein IQ motif containing GTPase activating protein 1 (IQGAP1) that positively regulates the MAPK pathway in NRAS mutated melanomas." (PMID 37325482, 2023). "Through the many interactions and binding partners, IQGAP1 is proposed to underlie progression of several types of cancers and more recently, drug resistance in melanoma." (PMID 29240845, 2017). "In melanoma, IQGAP1 may aberrantly associate in areas of retraction through an interaction with a component of the WRAMP complex initiated by cell adhesion to laminin." (PMID 29240845, 2017). "Taken together, our findings identify RAC1P29S as a constitutively active mutant and highlight DOCK2, p50GAP, and IQGAP1 as potential therapeutic targets for suppressing RAC1P29S-driven melanoma progression." (PMID 41034404, 2025). "The orthologous canine IQGAP1 protein is expressed in melanoma cell lines, and shows a high degree of sequence conservation in the ERK-interacting WW domain." (PMID 34822659, 2021). "We next examined ERK1/2 phosphorylation in the context of IQGAP1 depletion in the canine melanoma line that was most sensitive to MEK-inhibition (CMM5)." (PMID 28445541, 2017). "Rho inhibitors disrupt the WRAMP complex in human melanoma cells and IQGAP1 is known to interact with RhoA." (PMID 29240845, 2017). "We additionally examined the expression and localization of IQGAP1 in two canine mucosal melanoma cell lines." (PMID 28445541, 2017). "We observed that canine IQGAP1 is expressed and localizes to a similar extent in both human and canine melanoma by qPCR, Western blot, and immunofluorescence." (PMID 28445541, 2017). "We assessed proliferation in both canine melanoma cell lines with IQGAP1-targeting Cas9-CRISPR and note a consistent and statistically significant decrease compared to empty vector (EV) controls using four different sgRNAs in three biological replicates." (PMID 28445541, 2017). "This study explores the utility of expanding IQGAP1 targeted therapies to canine models of melanoma." (PMID 28445541, 2017). "Here, we aimed to identify the domains needed for localization of IQGAP1 to retracting edges and further characterize its role in single cell motility and melanoma tumor growth." (PMID 29240845, 2017). "Nothing is known of the domains needed for retraction localization and very little is known of IQGAP1 function in the actin cytoskeleton of melanoma cells." (PMID 29240845, 2017). "More recently, IQGAP1 was discovered to localize to retracting edges in mouse and human melanoma cell lines." (PMID 29240845, 2017). "In conclusion, we characterized localization of IQGAP1 deletion mutants and protein knock down phenotypes in mouse melanoma cells." (PMID 29240845, 2017). "We performed knock down studies in melanoma cells which have the unusual property where IQGAP1 localizes exclusively to areas of retraction." (PMID 29240845, 2017). "We previously reported that the subcellular localization of IQGAP1 was dependent on actin cytoskeleton retraction, and of the cell lines examined, IQGAP1 was most distinctly separated from WAVE2 in B16F10 mouse melanoma cells." (PMID 29240845, 2017). "We compared the RNA and protein expression of canine and human IQGAP1 in our cell lines compared to a panel of human BrafV600E melanoma cell lines." (PMID 28445541, 2017). "Our studies demonstrate that IQGAP1 has tumorigenic properties in melanoma and show that intracellular localization, likely as part of the WRAMP complex, is dependent on GRD and CT domains." (PMID 29240845, 2017). "We initially characterized the presence and localization of IQGAP1 in primary canine mucosal melanomas, observing that there does appear to be increased IQGAP1 expression, particularly co-localizing with melanocytes as well as at the tumor edge." (PMID 28445541, 2017).
melanoma (continued). "We propose that the GRD and CT domains regulate IQGAP1 localization to retracting actin networks to promote a tumorigenic role in melanoma cells." (PMID 29240845, 2017). "Taken together, these results classify RAC1P29S as a constitutively active, gain-of-function mutant and an oncogene that transduces upstream signals to effectors such as IQGAP1, thereby promoting melanoma progression through enhanced proliferation, invasion, and epithelial-to-mesenchymal transition." (PMID 41034404, 2025). "Furthermore, inhibition of IQGAP1 function in canine mucosal melanoma cell lines, either by CRISPR-Cas9 mediated gene knockdown or by competitive inhibition from a WW domain peptide mimetic results in growth inhibition and reduced phospho-ERK." (PMID 34822659, 2021). "IQGAP1 is known to be elevated in various cancers, and could serve as a potential therapeutic target, not only in melanoma but also in other cancers with hyper-activated MAPK signaling." (PMID 30026510, 2018). "Our results highlight the relevance of cytoplasmic lncRNA for oncogenic signaling pathways, and suggest that MIRAT and its protein-binding partner IQGAP1 may serve as potential therapeutic targets in melanoma through their modulation of the MAPK pathway." (PMID 30026510, 2018). "While promoting activity of RhoA, IQGAP1 may also decrease activity of Rac1 in the cell tail during melanoma migration, which may require interactions with C-terminal domains of IQGAP1." (PMID 29240845, 2017). "While there seems to be a modest difference in the absolute expression of IQGAP1 between human and canine melanoma cell lines (human cell lines express higher levels), the localization to the cytoplasm and the cell periphery is very similar based on immunofluorescence." (PMID 28445541, 2017). "To investigate whether IQGAP1 is a potential target in canine melanoma, we examined the expression and localization of IQGAP1 in primary canine melanomas and canine oral melanoma cell lines obtained from the University of California-Davis." (PMID 28445541, 2017). "With the observation of the largely conserved IQGAP1 sequence, we hypothesized that targeting IQGAP1 in the canine melanoma model should be an effective therapy in controlling neoplastic cell populations." (PMID 28445541, 2017). "These differ in their fusion endpoints from the OCLN–RASGRF1 and IQGAP1–RASGRF1 fusions reported here from a cholangiocarcinoma and a melanoma, respectively (although the segment of OCLN in both OCLN–RASGRF1 fusions is the same)." (PMID 40615519, 2025). "To test the importance of IQGAP1 in metastasis in vivo, we first created stable IQGAP1 knockdowns in MA2 melanoma cells using miR30-based shRNAs (sh1 and sh6), along with control cells expressing shRNA against firefly luciferase (shFF)." (PMID 32051509, 2020). "In this study, we identify a novel cytoplasmic intergenic lincRNA (MIRAT), which is upregulated following prolonged MAPK inhibition in NRAS mutant melanoma and modulates MAPK signaling by binding to the MEK scaffold protein IQGAP1." (PMID 30026510, 2018). "IQGAP1 is a signaling scaffold that regulates oncogenic ERK1/2 MAPK signaling in human Ras- and Raf- driven cancers, including melanomas." (PMID 28445541, 2017). "Here we examine localization of IQGAP1 deletion mutants to retraction versus protruding cell areas and describe protein knock down phenotypes in B16F10 mouse melanoma cells." (PMID 29240845, 2017). "Our studies suggest that IQGAP1, resulting from aberrant C-terminal localization with the WRAMP complex or other pathway in cell tail retraction, plays a tumorigenic role in melanoma." (PMID 29240845, 2017). "IQGAP1 localization is restricted to retraction in B16F1 and B16F10 mouse melanoma cell lines, and part of the WRAMP complex in the WM239A human melanoma cell line." (PMID 29240845, 2017).
melanoma (continued). "IQGAP1 localizes to areas of retraction in B16F1 and B16F10 mouse melanoma cell lines, and among the Wnt-receptor-actin-myosin-polarity (WRAMP) complex in the WM239A human melanoma cell line." (PMID 29240845, 2017). "Together, these results imply that targeting upstream regulators such as DOCK2 and downstream effectors, such as IQGAP1, could be effective therapeutic strategies for counteracting RAC1P29S-mediated melanoma progression and resistance to targeted therapies." (PMID 41034404, 2025). "Using spontaneously occurring primary canine mucosal melanoma samples (n = 4) from previously non-treated animals and normal canine mucosal samples for comparison (n = 2) we performed IQGAP1 immunohistochemistry." (PMID 28445541, 2017). "A number of studies link IQGAP1 to cancer through roles in tissue invasion, alterations in cell-cell junctions, angiogenesis, cell proliferation and more recently, resistance to a BRAF inhibitor used to treat melanoma." (PMID 29240845, 2017). "In a previous study, we discovered that IQGAP1 preferentially localizes to retracting areas in B16F10 mouse melanoma cells, not areas of membrane ruffling and lamellipodium protrusion." (PMID 29240845, 2017). "In neuroblastoma cells, the phosphomimetic mutant increased neurite outgrowth while the alanine substitution had no discernable effect, highlighting distinct IQGAP1 regulation in melanoma cells." (PMID 29240845, 2017). "Here we examined IQGAP1 mutant localization and knock down effects in B16F10 mouse melanoma cells." (PMID 29240845, 2017). "Thus, similar to other non-cancer and cancer cell types, knockdown of IQGAP1 in mouse melanoma cells decreased cell proliferation." (PMID 29240845, 2017). "Our studies support a model where the preferred localization in melanoma is through the C-terminus with binding partners in areas of actin retraction; however, when the C-terminus interaction is disrupted, interaction through the CHD domain may re-localize IQGAP1 to actin network protrusion." (PMID 29240845, 2017).